CCNB1 (cyclin B1)
Diseases named in the same sentence as CCNB1 in open-access papers (continued):
Sharing a sentence is not in itself a finding about the gene and the disease.
ovarian carcinoma (continued). "In this study, we found that CD83 associated with MAP3K7 and activated MAPK cascades to further regulate FOXO1/p21/CDK2/CCNB1 and STAT3/DKK1 signaling pathways, thus activating proliferation and spheroid formation of ovarian cancer cells." (PMID 32823589, 2020). "Our study revealed gene depletion across a number of molecular components involved in the spindle assembly checkpoint and mitotic regulation, including BUB1, CCNB1, CENPE and CENPF in paclitaxel resistant ovarian cancer cell lines." (PMID 29618387, 2018). "SAHA treatment induced apoptosis and reduced migration, invasion and lamellipodia formation in the ovarian carcinoma cells; furthermore, SAHA decreased expression of Cyclin B1 and CDC2P34 mRNA, and downregulated CDC2P34, Erk1/2, CyclinB1 and MMP-9 proteins." (PMID 24236158, 2013). "Protoapigenone exhibits a substantial cytotoxic potential on human ovarian cancer cells by inhibition of SKOV-3 and MDAH-2774 cells at the G2/M and S phases of the cell cycle by lowering the expression of p-cyclin B1, cyclin B1, p-Cdk2, and Cdk2 and boosting the inactive p-Cdc25C expressions." (PMID 36386196, 2022). "The interaction between Cyclin B1 and FOXM1 was particularly pronounced in UCEC and ovarian cancer." (PMID 35672443, 2022). "Moreover, CD83 functions through the activation of MAP3K7-MEK1/2-ERK1/2 cascades to further regulate downstream FOXO1/p21/CDK2/CCNB1 and STAT3/DKK1 signaling pathways, thus activating proliferation and spheroid formation of ovarian cancer cells, respectively." (PMID 32823589, 2020). "We identify the activated TAK1-MEK1/2-ERK1/2 signaling, increased CDK2/cyclin B1 expression, and reduced FOXO1/p21 levels in CD83-overexpressed ovarian cancer cells, indicating that MAPK-ERK1/2-FOXO1 axis is involved in the activation of ovarian cancer cell proliferation by CD83." (PMID 32823589, 2020). "XST-20 (25 and 50 μM) significantly reduced the protein level of CCNB1 and PLK1 while FOXM1 protein level was not changed in three ovarian cancer cell lines." (PMID 35680842, 2022).
bladder cancer (50 papers, 2011 to 2025). "CCNB1 is implicated in the development of bladder cancer, and its silencing has been shown to slow tumor growth and improve prognosis." (PMID 39456780, 2024). "Our data implicated that PBRM1 might suppress cyclin B1 and exert its tumor suppressing role by inducing cell cycle arrest in bladder cancer." (PMID 25978027, 2015). "However, cyclin B1 reduction has also been shown to cause cell cycle arrest at the G1 phase following celecoxib treatment in bladder cancer." (PMID 24403239, 2013). "Given that the antitumor effects of Cldn6, Anln, Ccnb1, and Melk have already been verified in bladder cancer, we used these four epitopes in our engineered OMVs." (PMID 38166929, 2024). "Liu and colleagues reveal that knockdown of GTSE1 reduces the expression of FOXM1 and CCNB1 in bladder cancer, indicating that GTSE1 positively modulates the expression and level of FOXM1." (PMID 38698443, 2024). "For example, myricetin inhibited the proliferation of T24 bladder cancer cells by down-regulating cyclin B1 and cyclin-dependent kinase cdc2 to induce cell cycle arrest in the G2/M phase." (PMID 36838963, 2023). "In this respect, our finding suggests that BA led to apoptosis and necrosis in human bladder cancer cells due to partial cell cycle arrest at the sub-G1 phase and G2/M phase via down-regulation of cyclin A, cyclin B1, Cdc2, and Cdk2." (PMID 33806566, 2021). "In bladder cancer cells treated with nimbolide, the G2/M phase cell cycle was arrested via the checkpoint kinase 2 (Chk2)/Cdc25C and Chk2/p21WAF1-related cyclin B1/Wee1 pathway." (PMID 33996570, 2021). "Down-regulation of CDK2, cyclin A, cyclin B1 and cyclin E contributed to the anti-proliferation effect of apigenin treatment in human bladder cancer T-24 cells." (PMID 33959508, 2021). "Chinese scholars reported that 40~80 μmol/L baicalein effectively kills bladder cancer cells by suppressing cell proliferation via downregulating cyclin B1 expression and decreasing CDC2 phosphorylation at Thr161 in bladder cancer T24 and HT1376 cells." (PMID 33996570, 2021). "In the present study, we found that cyclin A, cyclin B1, Cdc 2, and Cdk 2 were reduced by BA treatment in all three bladder cancer cells." (PMID 33806566, 2021). "Genistein inhibits bladder cancer cells proliferation by arresting the cell cycle at the G2/M phase via suppression of cyclin A and cyclin B1, and upregulation of CDKN1A (p21/WAF1)." (PMID 33996570, 2021). "We found that expression of cyclin B1 and Cdk1 are downregulated in bladder cancer cell lines treated with 9-ING-41." (PMID 31882719, 2019). "The results of the present study indicated that nimbolide induced the G2/M phase cell cycle arrest in bladder cancer cells via Chk2-Cdc25c-Cdc2/cyclin B1-Wee1 axis and Chk2-p21WAF1-Cdc2/cyclin B1-Wee1 axis." (PMID 31391858, 2019). "The present study suggests that nimbolide inhibited the proliferation of bladder cancer cells through G2/M phase cell cycle arrest mediated by both the Chk2-Cdc25C-Cdc2/cyclin B1-Wee1 pathway and Chk2-p21WAF1-Cdc2/cyclin B1-Wee1 pathway." (PMID 31391858, 2019). "To investigate the mechanistic effect of GSK-3 inhibitor 9-ING-41 in the blockage of cell cycle in bladder cancer cells, we examined the expression of G2/M regulatory proteins Cdk1 and Cyclin B1 in 9-ING-41-treated cells." (PMID 31882719, 2019). "The circRNA transcripts of the MYB Proto-Oncogene Like 2 (MYBL2) and Cyclin B1 (CCNB1) genes were significantly upregulated in the bladder cancer tissue samples." (PMID 31756170, 2019). "We found that expression of Cdk1 and Cyclin B1 proteins was significantly decreased in 9-ING-41-treated bladder cancer cells." (PMID 31882719, 2019). "Treatment with nimbolide decreased the protein levels of Cdc25c, Cdc2, and cyclin B1 and increased the expression of Wee1 and p21WAF1 in bladder cancer cells." (PMID 31391858, 2019).
bladder cancer (continued). "The results showed that the expression levels of ACTA2, CCNB1, CDC20 and VEGFA were associated with the prognosis of patients with bladder cancer." (PMID 30533316, 2018). "ATR-1 inhibited bladder cancer cell proliferation, arrested cell cycle in G2/M phase through up-regulation of p21 and down-regulation of cyclin B1, CDK1 and Cdc25c." (PMID 26931119, 2016). "Our data indicated that PBRM1 functions as a tumor suppressor in bladder cancer by repressing cyclin B1 expression." (PMID 25978027, 2015). "Mechanistically, WDR5 regulated various functions in bladder cancer by mediating the transcription of cyclin B1, cyclin E1, cyclin E2, UHMK1, MCL1, BIRC3 and Nanog by histone H3 lysine 4 trimethylation." (PMID 25656485, 2015). "In bladder cancer, cyclin B1 was also found increased and the recurrence rate was significantly higher in cyclin B1-high patients than that of cyclin B1- low patients." (PMID 25978027, 2015). "Gene CCNB1 seems related to aggressive forms of bladder cancer and cell proliferation, while the cyclin-dependent kinase CDK gene could be related to bladder tumor staging and prognosis." (PMID 36175974, 2022). "Therefore, the results of the multifactorial analysis show that cell cycle protein B1 (CCNB1) and cell division cycle 20 (CDC20) are risk factors for the prognosis of carcinoma of urinary bladder patients." (PMID 35280820, 2022). "Moreover, similar to our results, expression of cyclin B1 and Cdk1, mitotic entry regulatory proteins, were downregulated in bladder cancer cell lines treated with 9-ING-41." (PMID 34955846, 2021). "Taken together, this report indicated that PBRM1 exerted a tumor suppressing role and induced cell cycle arrest in bladder cancer, which might partly be due to suppressing cyclin B1." (PMID 25978027, 2015). "PBRM1 significantly repressed the expression of cyclin B1 in bladder cancer cells." (PMID 25978027, 2015). "Here we demonstrate that treatment of bladder cancer cells with Florin extracts results in an increase of cyclin B1/Cdc2 kinase activity as evidenced by increased levels of dephosphorylated Cdc2 kinase (activated Cdc2 kinase) in cells treated with Florin extracts." (PMID 21760824, 2011). "We found that TalaA blocked the transition from the G1 to S phase of bladder cancer cells and downregulated CCNA2 and CCNB1, which are well-known therapeutic targets for various cancers." (PMID 37866481, 2023). "Next, we performed the survival analysis of these eight genes (ACTA2, CDH1, CCNB1, FLNA, MCM5, MAD2L1, TAGLN and TPM1) in bladder cancer." (PMID 37274283, 2023). "Previous studies have demonstrated that inhibition of the PI3K/Akt pathway diminishes Cyclin B1 and CDK1 expression levels, thereby leading to the arrest of CC cells and bladder cancer cells in the G2/M phase." (PMID 37056992, 2023). "For example, KLF5 binds to a CCNE1 promoter proximal element in bladder cancer cells and KLF5 increases the expression of Ccnb1 and Mcm2 downstream of oncogenic Ras in fibroblasts." (PMID 32880368, 2020). "Our results suggest that GSK-3 positively regulates the expression of cyclin B1 and Cdk1, and treatment with 9-ING-41 leads to cell cycle arrest at G2-phase in bladder cancer cells." (PMID 31882719, 2019). "Survival analysis revealed that the expression levels of ACTA2, CCNB1, CDC20 and VEGFA were related to the prognosis of patients with bladder cancer." (PMID 30533316, 2018). "We performed protein-protein interaction analysis to select five important candidate genes (BUB1B, CCNB1, CDC25A, FBXO5, KIF20A, NDC80) regulated by PLK1 in bladder cancer cells using STRING software." (PMID 29246203, 2017). "Meanwhile CCNB1, CENPF and BUB1B genes were revealed to be positively co-expressed with ANLN in bladder cancer from three different datasets." (PMID 28600503, 2017).
bladder cancer (continued). "To evaluate the significance of the five proteins in bladder cancer, we investigated the relationship between the expression of the five proteins (BUB1B, CCNB1, CDC25A, FBXO5, NDC80) and clinicopathological features." (PMID 29246203, 2017). "We also observed that cyclin B1 was suppressed by PBRM1, indicating its tumor promoting effect in bladder cancer." (PMID 25978027, 2015). "Additionally, the correlation between CENPW expression and CDK1, CCNB1, and PCNA was further investigated in 10 bladder cancer tissue samples." (PMID 38213721, 2024). "In the current study, exposure of bladder cancer cells to isorhamnetin markedly reduced the expression of cyclin B1 and Wee1, without significant changes in the expression of Cdk1." (PMID 31590241, 2019). "Four genes (BUB1B, CCNB1, CDC25A and NDC80) were expressed at higher levels in bladder cancer tissues than in normal bladder tissues, but the expression of FBXO5 was lower in bladder cancer than in normal tissues." (PMID 29246203, 2017). "Atractylenolide I, an active sesquiterpene component extracted from Rhizoma atractylodis, inhibits T24 bladder cancer cell proliferation by arresting the cell cycle in the G2/M phase via downregulation of cell cycle-related proteins such as CDK1, cell division cycle 25C (CDC25c), and cyclin B1." (PMID 33996570, 2021).
glioma (47 papers, 2002 to 2025). A benign or malignant brain and spinal cord tumor that arises from glial cells (astrocytes, oligodendrocytes, ependymal cells). "Several central nervous system cancers are associated with altered levels of the G2/M phase cyclin B1 encoded by the CCNB1 gene." (PMID 39409884, 2024). "In addition, miR-181a-5p suppresses proliferation and induces apoptosis of glomerular mesangial cells by suppressing KLF6 and BCL2 expression via reduction of WNT/β-catenin signaling in human diabetic nephropathy and of glioma cell lines through suppression of the gene encoding for Cyclin B1." (PMID 33572377, 2021). "USP39 stabilizes Cyclin B1 expression by deubiquitinating it and promotes G2/M cell cycle transition and glioma cells proliferation." (PMID 40990019, 2025). "The deubiquitinating enzyme USP39 acts directly on Cyclin B1, promoting its stabilization and expression, the transition from the G2 to M phase of the cell cycle, the proliferation of glioma cells, and tumor growth in vivo." (PMID 40990019, 2025). "We have analyzed the level of Reg-2 and its newly identified targets that encode the cyclins CCND1, CCNE1, CCNE2, CCNB1, CCNA2, and the kinases PLK1 and AURKA in glioma tumors." (PMID 38238463, 2024). "Marchantin A-treated MCF-7 cells show suppressed cyclin B1 gene expression, whereas marchantin C-treated human A172 glioma cells show increased cyclin B1 levels, indicating the different methods of cell cycle regulations of the two compounds." (PMID 38140499, 2023). "Genes associated with the neuronal differentiation pathway (Pcsk9, Runx1, Cebpb, Fzd4, Wnt7a, Ascl1, Fzd2, Edn3, Olig2, and Gpc2), gliomas (Shc1, Cdk4, E2f2, and Ccnd1), and cell cycle (Bub1b, Bub, Ccnb1, Ccnb2, and Cdc20) were significantly downregulated." (PMID 36147849, 2022). "More importantly, silencing HAS3 or treatment with the anti-CD44 antibodies decreased the levels of the cell cycle-related proteins cyclin B1 and cyclin D1 in glioma cells, and CQ treatment further enhanced this effect." (PMID 33986244, 2021). "MIIP is able to interact with Cdc20 and suppress the activity of APC/CCdc20, thus blocking the degradation of two mitotic check proteins, cyclin B1 and securing, leading to impaired mitotic transition in glioma and colon cancer model." (PMID 31092266, 2019). "This genetic instability combined to persistent increased of cyclin B1 expression finally leads to the caspase-dependent mitotic cell death of glioma cells." (PMID 25544764, 2015). "Concomitantly, 2OHOA led to the arrest of 1321N1 cells in the G2/M phase of the cell cycle, with down-regulation of cyclin B1 and Cdk1/Cdc2 proteins in the three glioma cell lines studied." (PMID 23133576, 2012). "Tissue microarrays (TMAs) including I–IV grade clinical glioma samples was used to determine the prognostic effect of the CDC2/Cyclin B1 expression in gliomas on different grades." (PMID 18230152, 2008). "Cyclin B1 is overexpressed in gliomas, which correlates positively with pathological grading." (PMID 40990019, 2025). "Additionally, USP39 stabilizes Cyclin B1 by cleaving polyubiquitin chains, thereby promoting glioma progression." (PMID 39695108, 2024). "Additionally, small nucleolar RNA host gene 16 (SNHG16) suppressed the expression of p21, caspase-3 and caspase-9, while promoting cyclin-D1 and cyclin-B1 expression to inhibit apoptosis in glioma cells." (PMID 35601497, 2022).
glioma (continued). "Critically, ALDH3B1 and ALDH16A1 could also affect the expression of cyclin B1 and aurora A, G2/M cell cycle checkpoints that modulate glioma cells proliferation." (PMID 35116021, 2021). "Longer JQ1 treatment (24 h) further decreases CCNB1 in high-grade glioma cells." (PMID 32843692, 2020). "Furthermore, in the MYC-expressing human adult high-grade glioma cell line U305628 we again observed a significant downregulation of CCNB1 after 6 h of BRD4 inhibition via JQ1." (PMID 32843692, 2020). "CCNB1 was reported as a novel therapeutic approach against many tumors and may become novel therapeutic target for glioma." (PMID 26502731, 2015). "Silencing EPOR on glioma cells exposed to conventional treatments enhances senescence and induces a robust genomic instability that leads to caspase-dependent mitotic death by increasing the number of polyploid cells and cyclin B1 expression." (PMID 25544764, 2015). "Moreover, the Western blotting results showed that HYAL2 knockdown decreased the relative levels of the cell cycle-associated proteins CCNB1 and CCND1 in glioma cells, further suggesting that silencing HYAL2 could induce cell cycle arrest in glioma." (PMID 37568202, 2023). "In addition, we explored the CGGA, an independent glioma database, and validated expressions of the CCNB1/CDC42/MAPK7/CD44 gene signatures in WHO grade II, III, and IV GBM tumors using the Analysis of variance (ANOVA), with p < 0.05 considered statistically significant." (PMID 35008426, 2022). "Western blot results revealed that following β-sitosterol treatment, the levels of cyclin B1 and CDK1 were reduced, and the effect was concentration dependent, indicating that β-sitosterol induced G2/M phase arrest in glioma cells." (PMID 38143380, 2023). "Accordingly, western blotting showed that overexpression of LIMD1-AS1 resulted in higher Cyclin B1, Bcl-2, N-cadherin, and ZEB1 expression at protein levels in SF126 glioma cells." (PMID 37385987, 2023). "It promotes apoptosis in glioma cells by inducing G2/M cell cycle arrest by inhibiting the phosphorylation of CDK1 and the activity of the CDK1/cyclin B1 complex." (PMID 35694267, 2022). "Other co-expressed genes are also involved in the progression of glioma, such as KIF2C, DLGAP5 and CCNB1." (PMID 36040678, 2022). "The upregulation of CCNB1, CDK1, CXCL8, IGFBP3, MYBL2, SERPINE1 also notably indicated poor overall survival of glioma patients (HR>1, P=0.000<0.05)." (PMID 34512164, 2021). "Cur markedly decreases CDK1 in human glioma cells and downregulates CDK1 and cyclin B1 in human colon cancer Colo 205 cells." (PMID 34572508, 2021). "Consistently, IHC staing of CCNB1, CCND1, and CDK4 of the 21 glioma specimens confirmed that the protein expression levels of these cell cycle gene are correlated with PRMT2 in different grades of gliomas." (PMID 30382083, 2018). "CCNB1 and CDC2 play important roles in the proliferation of Glioma cells, the expression of PTTG1 is correlated with poor prognosis in Glioma patients, and aberrant splicing of CDKN3 increases proliferation and migration in Glioma cells." (PMID 21698123, 2011). "Moreover, ESURATAG-GS expression positively correlated with protein expression of cell cycle regulator, Cyclin B1 and negatively correlated with cell cycle inhibitor, PTEN, confirming the role of ESURATAG-GS in cell cycle progression in gliomas." (PMID 40718795, 2025). "In the present study, sempervirine inhibited the activity of CDK1 and increased the expression of cyclin B1, we thus conjectured that sempervirine might affect CDK1-Cyclin-B kinase activity of glioma cells, and resulted in distinct cell cycle perturbation." (PMID 34916946, 2021). "In our previous study, we showed that CCNB1 and KIF11 are upregulated in human and canine glioma." (PMID 31475119, 2019).